MTOR (mechanistic target of rapamycin kinase)
Diseases named in the same sentence as MTOR in open-access papers (continued):
Sharing a sentence is not in itself a finding about the gene and the disease.
tumor (continued). "At that time, case reports showed that mTOR-targeted therapy could be of value because this signaling pathway is usually strongly active in this tumor type." (PMID 31309284, 2020). "Therefore, the TCS/mTOR pathway gene sequencing in tumor patients can be used to guide clinical drug therapy." (PMID 32175074, 2020). "There is growing evidence of a significant role of ETV7 in the mTOR signaling pathway, which involves the assembly of the mTOR3 complex to stimulate cell proliferation and prevent cell damage by rapamycin, a common anti-tumor agent." (PMID 33424926, 2020). "Targeted mTOR inhibitory therapies are more complex and tumour specific." (PMID 32899149, 2020). "Additionally, IHC staining showed that expression of PI3K, AKT and mTOR was decreased in the MNAT1-knockdown xenograft tumor tissues." (PMID 33272245, 2020). "To determine whether the activation of the PERK/ eIF2α/ATF4/CHOP signaling pathway and inactivation of the AKT/mTOR signaling pathway were involved in CCT020312-induced tumor inhibition, we performed western blotting and IHC." (PMID 32508655, 2020). "For example, the activation of PI3K/AKT/mTOR and other carcinogenic pathways is related to the changes of bioenergy pathways such as glycolysis, fatty acid and glutamine metabolism, which provides a new target for tumour therapy." (PMID 32567187, 2020). "Activation of the PI3K/AKT/mTOR pathway contributes to the development of tumor." (PMID 33123313, 2020). "The mTOR pathway, on the other hand, stimulates systemic and local accumulation of neutrophils, which might outcompete macrophages and drive tumor evolution toward another direction." (PMID 33343560, 2020). "Specifically, we wanted to explore this combination in RCC due to known efficacy of mTOR inhibition and predicted additive and potentially synergistic activity with lenalidomide, as well as other tumour types where we might encounter promising efficacy signal." (PMID 32704173, 2020). "The mTOR signaling pathway is hyperactivated during carcinogenesis and tumor progression." (PMID 32899752, 2020). "As ERK and PI3K/Akt/mTOR signalings are closely correlated with tumor growth and metastasis, we tested whether FAM83A exerted its function via these two pathways." (PMID 32218702, 2020). "MTOR, as an oncogene, is known to be related to tumor chemo-resistance." (PMID 31898515, 2020). "Similarly, in vitro culture of tumor-specific memory T cells under CR conditions enhanced anti-tumor functions, accompanied by the inactivation of mTOR signaling." (PMID 33613560, 2020). "In this study, we hypothesized to target the circulating tumor cell interactions with the bone vascular network by inhibiting the VEGFRs, and to block the mTOR signaling pathway to target the tumor colony formation and growth." (PMID 32140451, 2020). "Additionally, mTOR inhibition with rapamycin effectively suppressed tumor growth by down-regulating both pathways in vitro and in vivo." (PMID 33302367, 2020). "A recent investigation in medulloblastoma tissue, showed that a tumor driving pathway, e.g., mTOR activation can cross-talk with indolamin-desoxygenase (IDO) expression, which consecutively induces Treg cell expansion and immunosuppression of tumor-specific immune responses." (PMID 32117316, 2020). "FKBP8 is an endogenous inhibitor of mTOR, its degradation promotes tumor progression." (PMID 32467664, 2020). "Moreover, M2BPGi treatment induced tumour-promoting effects on HCC in vitro by activated mTOR signaling." (PMID 32624579, 2020). "However, combining IGF-1R inhibitors with BET inhibitors, or mTOR inhibitors, presents a synergistic effect on the inhibition of survival and tumor growth of ES cells both in vivo and in vitro." (PMID 32754598, 2020).
tumor (continued). "Results of the ex vivo screening indicated an apparent MAPK/PI3K signaling pathway switch in the tumor cells based on the high sensitivity of the cells to mTOR inhibition, MEK inhibition and partial response also to antifolate abitrexate, BRAF and EGFR inhibition." (PMID 32576176, 2020). "Moreover, cellular mTOR cascade has been proved to favor the anti-tumor effect and immune cells metabolic activity." (PMID 32483450, 2020). "And the efficacy of mTOR inhibitor was promising in a phase II clinical trial which could inhibited the proliferation of GC cells and delayed tumor progression." (PMID 32769866, 2020). "In conclusion, we describe a tumor suppressor role of miR-100 and miR-125b in association with CSCs of HCC that involves the inhibition of IGF2 expression and resultant suppression of the IGF2-mediated PI3K/AKT/mTOR pathway." (PMID 33293585, 2020). "Thus, mTOR inhibitors have been widely studied and employed clinically in order to suppress tumor growth and sensitize cells to anticancer drugs." (PMID 32927648, 2020). "Furthermore, in vivo model in NOD/SCID mice also confirmed lower mTOR activity, Shh expression, reduced stemness markers and upregulation of apoptotic molecules in Neu2-overexpressed tumor tissue samples." (PMID 32575925, 2020). "Simultaneous blocking of PI3 K, AKT, and mTOR is an effective method of tumor suppression by promoting prolonged AKT, S6K1, and 4E-BP1 dephosphorylation, and induction of apoptosis, which may reduce symptoms as well as improve patient response." (PMID 31586300, 2020). "However, the molecular underpinnings and/or functional mediators of mTOR complexes in disease progression, and especially in tumor microenvironment conformation, remains poorly understood." (PMID 32923403, 2020). "Lysophosphatidic acid (LPA), a potent lipid mitogen generated via autotaxin (elevated in ccRCC), can modulate tumor progression but its role in altering chemotherapeutic sensitivity to mTOR inhibitors is unclear and thus is the focus of the studies presented herein." (PMID 32492043, 2020). "The decrease in tumor expression of p-class I PI3K/p-mTOR/p-p70S6K and increase of p-ERK validated the results using bioinformatics analysis and confirmed the observation in vitro, further highlighting the role of mutant HRAS in cisplatin sensitivity of T24 xenografts in response to pterostilbene." (PMID 33036162, 2020). "To determine the potential responsiveness to inhibition based on target networks identified by ssGSEA, we employed cell viability assays combining a FGFR inhibitor and a mTOR inhibitor in four HPV positive tumor cell lines with relatively high expression of E2/E4/E5 validated using RT-qPCR." (PMID 32848210, 2020). "PI3KCA acts on PI3K/AKT/mTOR pathway and is important for cell proliferation and tumor growth." (PMID 32373525, 2020). "In addition, several members of the SLRP family also function as tumor suppressors via regulating PI3K/Akt/mTOR pathway 24-26." (PMID 33033506, 2020). "In conclusion, increased phosphorylation of STAT3 in tumour‐conditioned microglia upregulates the expression of IL‐10 and IL‐6 in an mTOR‐dependent fashion with a concomitant reduction in expression of IL‐12 mediated by reduced phosphorylation and nuclear translocation of NF‐κB." (PMID 32567735, 2020). "In addition, AKT was also reported to play a key role in the progression of BC 42, and the activation of the PI3K/AKT/mTOR signaling pathway contributed to tumor progression and suggested poor clinical prognosis in BC patients." (PMID 32201512, 2020). "Therefore, an investigation of different processes involved in tumor development and progression interacting with the mTOR pathway is warranted." (PMID 31947591, 2020). "Furthermore, the phosphorylation of AKT and mTOR was significantly decreased in tumor tissues transfected with miR-660-5p inhibitor than in the inhibitor NC and blank groups." (PMID 33146288, 2020).
tumor (continued). "Besides, the expressions of p-AKT and p-mTOR in the tumours formed by E2F7-knockdown cells were decreased compared with the control cells, whereas the expression of PTEN was significantly increased." (PMID 32814835, 2020). "So mTOR inhibition affected almost exclusively later steps in tumor cell survival." (PMID 32373532, 2020). "Among extrinsic factors, the most prominent one is interferon-γ release by immune cells, while there are several tumor intrinsic factors such as activation of the mechanistic target of rapamycin (mTOR), mitogen-activated protein kinase (MAPK) and Myc pathways that can increase PD-L1 expression." (PMID 33114576, 2020). "BMI ≥ 35 vs. <25 kg/m2 was associated with a higher level of normalized p-mTOR expression in ER− tumor (191.2%, 95% CI = 10.5%–667.9%, P = 0.031), but not in ER+ tumors." (PMID 33024820, 2020). "Thus, the tumor suppressors that negatively regulate mTOR (PTEN, AMPK, LKB1, and TSC1/2) will initiate autophagy machinery while, on contrary, oncogenes that activate mTOR (class I PI3K, Ras, and AKT), will inhibit autophagy." (PMID 33297472, 2020). "Moreover, circHIPK3 knockdown suppressed tumor growth in vivo by inactivating the AKT/mTOR signaling pathway." (PMID 33817257, 2020). "After treatment with tyrosine kinase inhibitors, dying sensitive melanoma and lung cancer cells secrete into the extracellular space components that stimulate chemoresistance and metastasis of recipient tumor cells due to activation of the PI3K/AKT/mTOR pathway." (PMID 33114182, 2020). "The PI3K/AKT/mTOR pathway is also a key signaling pathway for tumor development." (PMID 32976685, 2020). "Autophagy also interacts with the mTOR pathway in tumor cells." (PMID 31912667, 2020). "Restored expression of EZH2 could reactivate AKT/MTOR pathway in the tumours formed by inhibiting PTEN." (PMID 32814835, 2020). "The role of the PI3K/Akt/mTOR (phosphoinositide 3 kinase/Akt/ mammalian target of rapamycin) pathway in cell cycle promoting has been proposed as a common intracellular signal transductor between AD and neoplasms." (PMID 32046139, 2020). "DCA and AZD7545 both prevented PDH phosphorylation in H460par and H460res cells, but activated AMPK, induced cell death and inhibited clonogenic growth only in H460res cells, thereby validating PDH kinases as a therapeutic target in tumor cells with mTOR-mediated therapy resistance." (PMID 32943635, 2020). "Much like chemotherapies, mTOR inhibitors would be expected to reduce tumor growth and metastasis; however, chronic treatment may result in the unintended propagation of a more aggressive disease, by fueling the accumulation of BCSCs." (PMID 32427827, 2020). "Conversely, tumor cell metabolism can also promote tumor growth through the mTOR pathway." (PMID 32175074, 2020). "It mediates its action through insulin-dependent and AMP-activated protein kinase (AMPK)-dependent effects, by selectively targeting CSCs, reversing multidrug resistance and inhibiting tumour metastasis and acts on mammalian target of rapamycin (mTOR) pathway inhibition." (PMID 32503256, 2020). "In summary, eIFs integrate the signals from the PI3K/AKT/mTOR pathway, which may be a promising target for tumor therapy in future." (PMID 33066449, 2020). "Indeed, data obtained in other solid tumors showed that inhibition of both mTOR signaling and Bcl-2 family activity did trigger in vivo tumor regressions." (PMID 33071785, 2020). "Akt-mTOR inhibition was detected in GDC-0349-treated xenograft tumor tissues." (PMID 33154352, 2020). "Moreover, the tumor phenotype was linked to regulation of the nutrient sensing mechanisms, with suppression of AMPK and increased mTOR activity in normal mammary tissues and tumors." (PMID 32760734, 2020).
tumor (continued). "Furthermore, we report that TTK regulates the proliferation and apoptosis of tumor cells through the Akt‐mTOR pathway." (PMID 32530571, 2020). "In addition, components in mTOR signaling also appeared to be consistently regulated in all tumor clones with respect to the normal organoid clone." (PMID 33087703, 2020). "The MAPK and PI3K/AKT/mTOR pathways converge at several points; therefore, dual or upstream blockade of them may have synergistic effects and overcome tumor resistance to current small molecule inhibitors in development." (PMID 32754300, 2020). "However, further studies are warranted to understand mechanistically how β-catenin regulates mTOR activation in tumor DCs to induce IL-10." (PMID 32132993, 2020). "Since PDCD4 is known to regulate protein synthesis in tumor models and also act as a downstream component of the mTOR pathway, we postulated that it could have a role in molecular processes relevant to axonal function." (PMID 32747606, 2020). "Activation of mTOR can inhibit cell autophagy, leading to unlimited proliferation of tumor cells." (PMID 33194612, 2020). "Besides, it has been reported that targeting PI3K/AKT/mTOR-mediated autophagy strongly enhances the chemosensitivity of tumor cells." (PMID 32373608, 2020). "In addition to direct anti-neoplastic activity, there is growing evidence that agents targeting the PI3K/Akt/mTOR pathway have indirect anti-tumor activity mediated through the host immune response." (PMID 32612958, 2020). "mTOR is a key downstream gene in many signaling pathways, and its increased phosphorylation level can promote tumor cell growth and development, conversely reducing the phosphorylation level of mTOR can inhibit these pathways and then restrain the tumorigenesis and development of tumors 57,58." (PMID 33033527, 2020). "Our results, on the contrary, suggest that increase in abnormal CpG island methylation driven by HER2 is mediated by PI3K/AKT/mTOR pathway leading to enhanced proliferation and rapid tumor evolution with accumulation of CpG island hypermethylation that is not directly functional in BC pathogenesis." (PMID 32397602, 2020). "mTOR signaling has also been demonstrated to have an important role in T cell differentiation and activation and therefore may mediate the host anti-tumor immune response." (PMID 32523648, 2020). "In addition, tumor-associated pathways, such as apoptosis, PI3K/AKT/mTOR signaling pathway, JAK/STAT signaling pathway, and T cell receptor signaling pathway, were also highly enriched." (PMID 32850314, 2020). "Moreover, the secondary effects regarding mTOR suppression would lessen any invasive or migratory activity of tumor cells." (PMID 33552982, 2020). "Among them, mTOR plays a key role in tumor tumorigenesis and development." (PMID 32175074, 2020). "Indeed, hypoxia inhibits downstream signaling and mRNA translation initiation of mTOR, resulting in tumor progression and hypoxia tolerance in advanced tumor settings." (PMID 32316260, 2020). "Indeed, we discovered that inhibiting mTOR in FGF19-overproducing LSQ resulted in significant tumor inhibition." (PMID 32111983, 2020). "In light of this evidence, it is not surprising that a more intense mTOR pathway deregulation is associated with increased tumor recurrence rates after surgical resection or liver transplantation, as well as with shorter survival." (PMID 32070029, 2020). "For example, attempts to inhibit glutamine transamination in glioblastoma, blocking the increased glutamine regulated signaling pathways (mTOR pathway), or by targeting c-myc regulated glutamine uptake were shown to induce significant cytotoxicity to tumor cells." (PMID 32670883, 2020). "According to the diverse metabolic effects of rapalogs and the individual variability of adaptation/resistance properties, we suggest that other metabolic inhibitors may be able to enhance the effects of mTOR inhibitors and reduce tumour growth." (PMID 32899149, 2020).
tumor (continued). "A recent study has found that enhanced glycolysis mediated by the mTOR pathway leads to stronger suppressive capacity of tumor-infiltrating M-MDSCs as compared with splenic M-MDSCs and that mTOR inhibition by rapamycin reduces the glycolysis, intratumoral level, and suppressive activity of M-MDSCs." (PMID 32793192, 2020). "Finally, PTEN is a tumor suppressor gene mutated in 9–23% of HPV-negative HNC, leading to oncogenic activity through the activation of the PI3K/AKT/mTOR signaling." (PMID 32561788, 2020). "A major source of resistance to trastuzumab in several tumours is the PI3K/AKT/mTOR pathway." (PMID 32410348, 2020). "In addition, hypoxia-inducible factor 1α (HIF-1α) and vascular endothelial growth factor (VEGF) are activated by CTHRC1 through activating the PI3K/AKT/mammalian target of rapamycin (mTOR) signaling pathway, which promotes tumor angiogenesis." (PMID 32848510, 2020). "The anti-proliferative effect of metformin in some tumor cell types is due to mTOR inhibition." (PMID 33537296, 2020). "In addition, tumor cell progression is stimulated by enhancing the mTOR signaling pathways through an increase in insulin-like growth factor 1 (IGF-1)." (PMID 31959179, 2020). "However, the enhancement of autophagy by the inhibitors of PI3K/AKT/mTOR signaling leads to tumor cell drug resistance, increased metabolic capacity, and antiapoptotic capacity, which is regarded as a cytoprotective adaptive reaction." (PMID 33123479, 2020). "Furthermore, Neu2-overexpressed tumor tissue samples showed a lower expression of Shh and mTOR at protein level than vehicle control." (PMID 32575925, 2020). "Recent studies also suggest that mTOR not only promotes intrinsic tumor cell growth and survival property, but may also contributes to regulation of an unfavorable tumor microenvironment that may further hinder treatment outcome." (PMID 32923403, 2020). "In addition, the activation of mTOR is more intense in the tumor edge, thus reinforcing its role in HCC proliferation and spreading." (PMID 32070029, 2020). "Tumor cells with high levels of miR-222 had activated AKT/mTOR axis." (PMID 33183321, 2020). "Hence, the effect of mTOR can be defined by combinations of a genetic lesion in a tumour cell, nutrient status and the environmental context." (PMID 31819196, 2020). "Mammalian target of rapamycin (mTOR) is a serine/threonine protein kinase, and the mTOR signaling pathway has been shown to regulate some cellular processes, including protein synthesis, cell growth, cell proliferation, cell death, and tumor angiogenesis." (PMID 33344645, 2020). "Excessive activation of mTOR signaling pathway was ubiquitous in tumor cells." (PMID 32595698, 2020). "Indeed, tumor cells acquire resistance to mTOR inhibitors by rewiring their signaling to activate compensatory pathways that enable survival under selective pressure." (PMID 32665551, 2020). "PG2 inhibit tumor PD-L1 expression through modulating the AKT/mTOR signaling pathway." (PMID 32308547, 2020). "Recently, research data have indicated that inhibiting regulators of the PI3K/AKT/mTOR pathway may not only suppress tumor growth but also enhance tumor immunosurveillance by affecting immune cell effectors." (PMID 32414171, 2020). "Moreover, numerous studies have demonstrated that USP10 inhibited mTOR activation and promoted oncogene-induced senescence to exert a tumor-suppressive effect." (PMID 33178587, 2020). "mTOR activation was responsible for the PDP1-induced tumor cell proliferation and invasion in PDAC." (PMID 32782783, 2020). "For example, using iopromide as the contrast agent, CEST MRI revealed a statistically significant increase in tumor pHe (~0.10 pH unit) within the first day of the treatment of everolimus (RAD001), an mTOR inhibitor, correlating well with the decreased tumor growth rate." (PMID 33374213, 2020). "Rapamycin could block targets known to be downstream of mTOR such as inhibition of p70S6K activity to inhibit metastatic tumor growth." (PMID 32655659, 2020).